H19 (H19 imprinted maternally expressed transcript)
Diseases named in the same sentence as H19 in open-access papers (continued):
Sharing a sentence is not in itself a finding about the gene and the disease.
tumor (continued). "H19 and miR-675 may have a dual mechanism depending on the tumor microenvironment or tumor type." (PMID 28212565, 2017). "Finally, the influence of H19 on tumor induction was investigated." (PMID 31223144, 2017). "Furthermore, the clonogenicity, migration and sphere-forming ability remained substantially lower in the cells isolated from the shH19 tumor xenografts of the second transplantation, with 66.8% knockdown efficiency of H19 in comparison with the cells from the NTC tumor xenografts." (PMID 28102845, 2017). "Thus, it was of interest to evaluate the impact of partial hepatectomy on tumor growth as well as to evaluate the correlation between H19 and HGF levels in tumors and in the liver after hepatectomy in the animal models being used to evaluated BC-819 therapy of liver metastases." (PMID 26623562, 2016). "However, studies have also indicated that H19 is a tumor suppressor in vivo." (PMID 26637808, 2016). "Additionally, H19 is involved in tumor development, progression, metastasis, and drug resistance." (PMID 27193186, 2016). "Furthermore, we found that H19 could well distinguish early stage tumor, with a much higher sensitivity and specificity than conventional biomarkers." (PMID 26096073, 2015). "Several lines of evidence indicate that H19 could play a role in tumor invasion and angiogenesis." (PMID 25972893, 2015). "Therefore, we examined whether overexpression of H19 could enhance tumor growth and metastasis in vivo by subcutaneously injecting SGC7901/H19 cells into nude mice and monitoring tumor growth weekly." (PMID 24810858, 2014). "H19 is a tumor suppressor gene and its knockdown may play a role in HCC development." (PMID 25165821, 2014). "Additionally, H19 overexpression enhanced tumor growth in Hep3B cells." (PMID 25543668, 2014). "The observation that H19 downregulation simultaneously suppresses proliferation and apoptosis of JAR cells suggests a putative dual functionality of H19 in choriocarcinoma cell lines and may explain the debate over whether H19 is a tumor suppressor or a tumor promotor in trophoblast tissue." (PMID 23711233, 2013). "Thus, it remains controversial whether H19 functions as a tumor promotor or a tumor suppressor, and it is possible that H19 plays differential roles depending on tissue type and/or developmental stage." (PMID 23711233, 2013). "Interestingly, the effect of the 91H RNA on Igf2 derepression observed here in complementation studies, may explain the Igf2 derepression occurring in many tumours where 91H RNA was found to accumulate while the H19 gene is maintained in a repressed state." (PMID 22662250, 2012). "There is evidence suggesting H19 may also play a role in tumor suppression." (PMID 21489289, 2011). "Thus, even individuals with an H19-expressing tumor, for example, may contain some cancer cells that have downregulated or abrogated H19 expression via mutation." (PMID 21162716, 2010). "H19 may be a tumor suppressor gene involved in head and neck carcinogenesis." (PMID 19737423, 2009). "Furthermore, silencing H19 expression attenuates tumor growth in vivo." (PMID 17786216, 2007). "Next, we questioned whether the H19 message affects tumor growth of other cell lineages." (PMID 17786216, 2007). "Overexpression of H19 activates the PI3K/AKT pathway and silences tumor suppressor genes such as let-7b through sponging target genes and subsequently inducing EMT." (PMID 41890909, 2026). "H19, NEAT1, and MALAT1 showed significantly altered expression in tumor tissue, as well as non-tumor tissue before and after nCRT." (PMID 41751809, 2026). "The lncRNA H19/miR-675-5p/PFKFB3 axis drives glycolysis in CAFs and enhances proliferation, migration, and tumor growth in oral squamous cell carcinoma (OSCC)." (PMID 41361062, 2025). "Considering the tumor-suppressive role of H19 in ICCA, we engineered an oncolytic adenovirus to overexpress H19." (PMID 41208889, 2025).
tumor (continued). "The H19 expression cassette was inserted into the viral E1B55-kDa deletion region, which enhances tumor-selective cytotoxicity 27, generating the recombinant virus SD55-H19 (with SD55-EGFP serving as a control)." (PMID 41208889, 2025). "As with H19, CCAL can also be transferred from CAFs to cancer cells via exosomes, facilitating the propagation of chemoresistance throughout the tumor." (PMID 40781643, 2025). "H19 is an imprinted lncRNA with increased expression reported in CRC in both serum samples and tumor tissue, contributing to invasion, metastasis, and poor prognosis." (PMID 41463069, 2025). "In prostate cancer, lncRNAs such as H19 and PCAT29 play critical but distinct roles in modulating tumor behavior." (PMID 40242248, 2025). "This stabilization of HIF-1α enhances glycolysis and apoptosis resistance in tumor cells; Under hypoxic conditions, HIF-1α directly binds to the promoters of certain lncRNAs (e.g., H19, DARS-AS1) and induces their transcription." (PMID 40861273, 2025). "Many cellular processes in cancer stem cells (CSCs) that are known to initiate tumor formation can be regulated by lncRNAs such as MALAT1, ROR, HOTAIR, H19, UCA1 and ARSR." (PMID 39199690, 2024). "In renal cell carcinoma, the lncRNA H19 acts as a molecular sponge for miR-29a, derepressing HIF-1α expression and fostering tumor growth." (PMID 38279330, 2024). "Numerous lncRNAs and their sponged targets have been identified as both diagnostic and therapeutic targets in the development of GBM tumours, such as LINC02015, H19, KIAA0495, AC068888.1 and MALAT1." (PMID 38594690, 2024). "Mechanisms involving lncRNA H19 in chemoresistance include inducing EMT, activating oncogenic signaling pathways, and altering the tumor microenvironment." (PMID 38794196, 2024). "LncRNAs, such as HOTAIR, PCGEM1, H19, and UCA1, are dysregulated in many types of tumor tissues and can function either as oncogenes or tumor suppressors through regulating cancer cell growth, apoptosis, and invasion." (PMID 38195623, 2024). "H19 is a lncRNA widely considered an oncogene in various types of cancer, including EOC, and it is critically involved in tumor development, malignant progression, and chemoresistance." (PMID 38004379, 2023). "This miRNA targets oncogenes and important genes for the initiation and progression of the tumor, including Myc, RAS, E2F1, E2F5, LIN28, ARID3B, PBX3, HMGA2 and long non-coding RNA H19." (PMID 36833380, 2023). "H19, TCL6, CAM1-AS1, GAS5 and LOC389332 act as tumor-suppressors, and are instead, downregulated; in particular, H19 and TCL6 are negatively correlated with TNM stage, lymph node metastases and distant metastases." (PMID 37370817, 2023). "H19 or ILF2 depletion led to a drastic reduction in tumor volume, suggesting that H19 and ILF2 promote tumor progression." (PMID 37298108, 2023). "Up-regulated tumor-promoting lncRNAs such as MALAT1, UCA1, H19, HIF1A-AS2 and down-regulated tumor suppressor lncRNAs such as NBAT1, GASS, RNCR3, etc., all of which play an important role in the formation and malignant progression of gliomas." (PMID 37153654, 2023). "At the same time, H19 can act as a ceRNA to inhibit the expression of miR‐93a and increase the high expression of autophagy related genes (ATG7) in tumor cells, thus enhancing the sensitivity of prolactinoma to dopamine agonists." (PMID 37904679, 2023). "The expression of tumor suppressor LncRNAs including GAS-5 and MEG3 was significantly augmented in bharangin-treated cells, while this diterpenoid down-regulated oncogenic H19 LncRNA." (PMID 36770654, 2023). "Among HB without mosaicism, tumors with 11p15.5 alteration showed a higher IGF2 expression (P = 0.01) and a lower H19 and CDKN1C tumor suppressor expression (P = 5.3 x 10−8 and P = 4.0 x 10−3, respectively)." (PMID 37932266, 2023). "According to the proposed mechanism, let-7 was targeted by H19 in order to enhance the expression of HMGA2, a crucial regulator of tumor metastasis." (PMID 37635248, 2023).
tumor (continued). "However, it is controversial as to whether H19 is a tumor suppressor or a tumor promoter." (PMID 35674441, 2022). "Our data show that tumor cell viability and colony formation were significant in A549 and VMRC-LCD cell lines in which H19 was overexpressed (p = 0.001)." (PMID 36139647, 2022). "Recent study showed TGF-β and H19 axis via Sox2 importantly regulates hepatocarcinogenesis, regardless its lower expression level in HCC tumor tissue." (PMID 36578923, 2022). "In the analysis of the relative expression level of the tested long non-coding RNA H19, MALAT1 and gene BCL2 we obtained statistically significant levels when comparing tumor versus normal adjacent samples." (PMID 35723379, 2022). "In the cellular senescence pathway, the principal targets of H19 are p16 and ARF, two tumour suppressors molecules, biomarkers of ageing that are up-regulated in our study." (PMID 35205253, 2022). "For example: HOTAIR, PVT1, H19 and MALAT1 showed oncogenic effect, while MEG3 and GAS5 have tumor suppressor effect." (PMID 35668225, 2022). "Both pathways utilize dysregulation of 11p15 genes as a driver of oncogenesis, either resulting in a tumor arising directly in isolation through LOH of 11p15, or indirectly via clonal nephrogenesis with perturbation of 11p15 by GOM of H19/IGF2:IG DMR." (PMID 35804856, 2022). "Over 70% of BC tumours, including ER+ and ER-, HER2+ and HER2-positive tumours, have highly expressed H19." (PMID 36212140, 2022). "Unsurprisingly, some common and vital lncRNAs that promote tumor progression are at the forefront of the H3K27ac signal, such as MALAT1, H19, and CCAT1." (PMID 35311149, 2022). "LncRNAs regulate EMT process by targeting EMT-related signalling pathways directly (i.e., H19, HOTAIR, ZEB2-AS1, LincRNA-p21 and SNHG1), or function as ceRNAs (i.e., H19, HOTTIP, MALAT1, SNHG1 and SNHG6) for tumour suppressive miRNAs." (PMID 36310592, 2022). "As example, CASC2, TSLC1-AS1, and ADAMTS9-AS2 are tumor suppressor lncRNAs, while linc-POU3F3, HOTAIR, and H19 function to promote GBM cell cycle progression." (PMID 35668225, 2022). "Therefore, it remains unclear whether H19’s functional role is tumor suppressive or oncogenic." (PMID 36246634, 2022). "H19 is high-expressed in CRC tissues, and overexpression of H19 can substantially promote epithelial-mesenchymal transition (EMT) and accelerate tumor growth in vivo." (PMID 34226413, 2021). "For the multi-functions of ncRNAs in tumor angiogenesis, miR-21, miR-93, circ-ATXN1, and circ-0056618 participate in regulating several key aspects of this course and H19 involve in the whole processing." (PMID 34616746, 2021). "Our final panel consisted of seven up‐regulated DElncRNAs (CCAT1, CCAT2, H19, HOTAIR, HULC, MALAT1, PCAT1), which were also known as oncolncRNAs and three down‐regulated lncRNAs (MEG3, PTENP1, and TUSC7) as tumor suppressor lncRNAs (tslncRNAs)." (PMID 33094859, 2021). "Another group discovered that H19 expression was higher in GBC tissues than in normal bladder tissues, and was positively correlated with tumor size and lymphatic metastasis." (PMID 34421359, 2021). "Interestingly, H19 had been shown to inhibit Insulin Receptor Substrate 1 (IRS-1), reducing cell viability, migration, and invasion in TC, which supports the thesis that H19 may have a tumor suppressor role in TC cells treated with deacetylase inhibitors, leading to differentiation and cell death." (PMID 34108939, 2021). "LncRNA H19, FMR1-AS1, RUNX2-AS1, and Sox2ot have been studied for their roles in promoting tumor stem cells in different cancers." (PMID 34067896, 2021). "Other oncogenic lncRNAs such as H19, HULC, SNHG12, and HOTAIR also demonstrated their regulatory functions in promoting cancer cell proliferation, inhibiting apoptosis, and aggravating tumor progression." (PMID 34456631, 2021).
tumor (continued). "LncRNAs can be categorized as oncogenic or tumor suppressor lncRNAs according to their biological functions during carcinogenesis, such as the well-known MALAT1, ANRIL and H19." (PMID 31907020, 2020). "In the current study, H19 expression was positively correlated with activation of STAT3 signaling in PC cells, which has been reported to be involved in tumor initiation, stemness maintenance and chemotherapy resistance 22-24." (PMID 32626524, 2020). "H19 expression was also higher in stage III and IV NSCLC, while hsa-miR-21 expression was higher in stage I and II NSCLC when compared to non-tumor lung tissues." (PMID 32438606, 2020). "Indeed, the chromosome alterations affecting the H19, KCNQ1OT1, PLAGL1 and GNAS DMRs also affected one or more WT driver genes in all analyzed cases, and the chromosome variants affecting the MEST, GRB10 and MEG3 DMRs also affected tumor driver genes in at least 83% of cases." (PMID 33217932, 2020). "Thus, H19 and miR-675 could have sequential effects leading to metastasis; H19 would favor the departure of cells from the primary tumor by promoting the EMT, while miR-675 would also favor a metastatic colonization and the development of secondary tumors by inducing the MET." (PMID 32610610, 2020). "For example, hypoxia has been shown to induce H19 expression in HCC cells, whereas knockdown of H19 attenuated HCC tumor growth." (PMID 32872482, 2020). "First, salivary lncRNA H19 levels are similar in both PDAC and non-tumor patients although the levels of several other lncRNAs are significantly different between them." (PMID 32272875, 2020). "Mechanistically, Wu T. and colleagues report that H19 is overexpressed in laryngeal squamous cell carcinoma (LSCC) and accelerates LSCC tumor progression through miR-148a-3p attenuation and DNMT1 enhancement." (PMID 33123473, 2020). "Cancer cell–derived lncRNA H19 targets endothelial cells to promote angiogenesis by modulating the production and release of VEGF, contributing to tumor growth." (PMID 33281872, 2020). "Therefore, H19 may modulate tumor growth through MIP-140-dependent iASPP." (PMID 32883200, 2020). "The methylation alterations at H19/IGF2:IG-DMR and KCNQ10T1:TSS-DMR detected in the tumor samples were generally more intense than those affecting the other imprinted loci." (PMID 33217932, 2020). "LncRNA H19 is a maternally imprinted gene that is highly expressed in PDAC tissues and is involved in tumor progression." (PMID 32257946, 2020). "H19 is an important oncogenic factor promoting the malignant behaviors of PDAC and other malignant tumors in humans by sponging specific miRNAs in a tumor origin-dependent manner." (PMID 32272875, 2020). "H19 knockout leads to increased tumor development and tumor multiplicity upon DEN, thus showing a tumor-suppressive effect of H19 in vivo and supporting their previous conclusions from in vitro models." (PMID 32429417, 2020). "In any cases, the expression of H19 due to the demethylation of its promoter leads to the enhancement of liver CSC activity, and thus the tumor resistance to doxorubicine treatment." (PMID 33291403, 2020). "Our results revealed that overexpression of H19 in HCT116 cells lead to more metastatic tumors in lung and larger tumor size compared to control group." (PMID 32698890, 2020). "To validate the expression pattern of H19, we analyzed 60 primary CRC specimens and corresponding adjacent non-tumor tissues from the tissue bank of the first affiliated hospital of Sun Yat-sen university by qRT-PCR." (PMID 32698890, 2020). "For instance, H19, HOTAIR, MALAT1, TUG1, GAS5, and CCAT1, were found to play important roles in tumor initiation and development 44-49." (PMID 32922554, 2020). "The mRNA expression of lncRNA H19 was markedly reduced in tumor-bearing mice after lncRNA H19 or TNFAIP8 knockdown, which likely contributed to its weaker ability to promote tumor growth." (PMID 32514245, 2020).
tumor (continued). "Actually, numerous lncRNAs function as oncogenes or tumor-suppressor genes, which were reported to be involved in metastasis and prognosis of HCC, such as MEG3, GAS5, HOTAIR, HULC, H19, and MALAT1." (PMID 31500187, 2019). "Again, the dysregulation of CEP55, CLDN4, CHAF1A, H19 and STEAP4 have been found to significantly correlate with CRC tumor stage, aggressiveness, metastasis and poor prognosis." (PMID 30823889, 2019). "To ensure the EPIC array data truly reflects the methylation profile at imprinted DMRs, we performed pyrosequencing for the H19, KCNQ1OT1, and FAM50B regions which confirmed that the tumour sample is 22–24% less methylated than the corresponding placenta." (PMID 31357948, 2019). "In this study, for the first time, we found that both lncRNAs H19 and MALAT1 showed high expression level in tumor specimens of GIST patients." (PMID 31827510, 2019). "In vivo, A549 cells with silencing lncRNA H19, overexpression of CDH1 or reduced CDH1 methylation exhibited low tumorigenicity, reflected by the smaller tumour size and lighter tumour weight." (PMID 31317666, 2019). "Tumor suppressive lncRNAs (GAS5, MEG3, FER1L4 and LINC00672) and oncogenic lncRNAs (CCAT2, BANCR, NEAT1, MALAT1, H19 and Linc-RoR) have been identified as key regulators of the established tumor suppressor or oncogenic pathways in EC." (PMID 30781521, 2019). "Increasing evidence shows that long non‐coding RNA H19 (lncRNA H19) and CDH1 methylation are involved in multiple tumours." (PMID 31317666, 2019). "It is demonstrated that HOTS acts as a tumor suppressor in vivo and that the levels of HOTS and H19 appear to be uncoordinated." (PMID 31277475, 2019). "In addition, H19 could also activate miR-200 and suppress tumor metastasis and EMT." (PMID 30105249, 2018). "In the first tumor transplantation, empty vector with NTC (Ctrl), H19 overexpression with NTC (H19), empty vector plus PDK1 knockdown (shPDK1), and H19 plus shPDK1 MDA-MB-231 cells were subcutaneously transplanted into nude mice (n=5)." (PMID 29106390, 2018). "We compared the expression levels of nine hypoxia-related lncRNAs39, 40, 41 (H19, HOTAIR, NEAT1, linc-ROR, UCA1, WT1, HINCUT1, LINK-A, LincRNA-p21) between tumor central and peripheral cells." (PMID 29106390, 2018). "When taking into account the different tumour subtypes, we detected 24 SNPs (in eight genes: ZDBF2, PEG10, MEST, H19, IGF2, MEG3, ZNF331 and HM13) exhibiting DI in at least one subtype compared to the normal tissue samples." (PMID 30297886, 2018). "Noticeably, high expression of H19 in CRC had a significant correlation with the tumor differentiation (P = 0.023) and depth of tumor (P = 0.007)." (PMID 30451820, 2018). "In contrast to H19 overexpression, knockdown of H19 expression in GH3 cells led to enhance growth of xenograft tumours." (PMID 30397197, 2018). "The mice injected with H19 cells formed apparently larger tumor masses than the mice injected with Ctrl cells, but shPDK1 markedly reversed the tumor volumes, indicating PDK1 was critical for H19-mediated tumor growth." (PMID 29106390, 2018). "Compared to the results for all tumour samples, significant DI of MEST was detected at the same SNP position in all subtypes except for BL, whereas HM13 and H19 were significantly deregulated in all but LumA." (PMID 30297886, 2018). "H19 overexpression enhanced the tumor growth in in vivo models of HCC, while H19 inhibition decreased." (PMID 30105249, 2018). "To study the role of H19 in CRC, we first detected its expression in 110 paired CRC tissues and para-tumor tissues." (PMID 30451820, 2018). "Among them, H19 and another five lncRNAs (HOTAIR, PVT1, MALAT1, GHET1 and HULC) were significantly higher in tumor tissues compared to matched normal samples." (PMID 29599934, 2018). "H19 has been reported to play a role in epithelial to mesenchymal transition (EMT), which is the initial key process required for tumor metastasis in certain cancer cells." (PMID 30410672, 2018).